MYC (MYC proto-oncogene, bHLH transcription factor)
Diseases named in the same sentence as MYC in open-access papers (continued):
Sharing a sentence is not in itself a finding about the gene and the disease.
tumor (continued). "These new developments in therapeutic targeting of MYC in cancer have broad implications in a challenging field where inhibition of MYC has been shown to result in tumor regression but has proven problematic to execute because of difficulties in delivery or specificity." (PMID 27081479, 2016). "Regarding our immunohistochemical studies, we would like to point out that, while we found only ~30% of tumor cells being labeled with MYC, two previous publications showed that MYC immunohistochemical reactivity is detectable in the majority of tumor cells in ALK + ALCL." (PMID 27821172, 2016). "Remarkably, the proliferation defects were fully reversible, suggesting that anti-MYC therapy could be used to treat human disease since tumor cells often apoptose upon MYC inhibition whereas normal cells simply fail to proliferate." (PMID 27081479, 2016). "Interestingly, MYC promotes the metabolic adaptation of tumor cells by activating genes important for mitochondrial biogenesis and function." (PMID 27455839, 2016). "Hence, identification and characterization of transformation-relevant target genes acting downstream of MYC is a prerequisite to understand molecular mechanisms of tumor development in which this oncogenic transcription factor is involved." (PMID 27313991, 2016). "Indeed, comparison of tumor and normal samples showed a significant proportion of MYC-target genes misregulated in KIRC and other cancers (Fisher's Exact -test adj." (PMID 27366943, 2016). "We speculate that rs55705857 increases MYC expression in a particular spatial and temporal context and therefore increases the probability of tumor formation." (PMID 27282637, 2016). "Immunstaining for the MYC-tagged GLI2A transgene product identified dysplastic GLI2A-expressing tumor cells adjacent to highly-proliferative GLI2A-negative gastric epithelial cells, and in situ hybridization of full-blown tumors revealed Hh target gene expression only in transgene-expressing cells." (PMID 26859571, 2016). "MYC and let-7 are key oncoprotein and tumor suppressor, respectively." (PMID 27409345, 2016). "However, other studies went on to show that MYC actually binds to thousands of genes and somehow only regulates a subset of them during tumor development." (PMID 27460974, 2016). "We therefore propose that small molecules capable of disrupting this interaction may represent a valuable approach to treat c-MYC-addicted tumours." (PMID 26729287, 2016). "Interestingly, dinaciclib, an inhibitor against CDK1, 2, 5, and 9 (IC50 1-4nM), but with less activity against CDK4, 6, and 7 (IC50 60-100nM), showed encouraging anti-tumor effect in preclinical studies of TNBC with potential selectivity for MYC driven tumors." (PMID 27486754, 2016). "Importantly, promoter affinity stratifies different biological processes that are regulated by MYC, explaining why tumor-specific MYC levels induce specific gene expression programs and alter defined biological properties of cells." (PMID 27460974, 2016). "Constitutive activation of MYC is required for oncogenesis and occurs in many human tumor cell lines indicating that deregulated expression of this oncoprotein may contribute to cancer formation." (PMID 27313991, 2016). "Notably, aggregating all tumor types for each clinical class, the discriminant transcripts show enrichment in MYC targets and genes involved in oxidative phosphorylation." (PMID 27535130, 2016). "Based on our previous findings, we hypothesized that MYC or CDC25B up-regulation may induce YWHAE down-regulation in GC or YWHAE down-regulation would induce CDC25B up-regulation in this neoplasia, which would also contribute to MYC overexpression." (PMID 27863420, 2016). "MYC locus genomic gain at 8q24 was observed in about 10% of O1 tumours." (PMID 27090007, 2016). "I-BET762 decreased PCa cell lines proliferation and reduced tumor burden in an in vivo model of a patient-derived tumor and these encouraging results might be due to MYC downregulation." (PMID 27651838, 2016).
tumor (continued). "To determine which molecular mechanisms could trigger MYC activation in O1 tumours, we looked for genomic, epigenetic and post-transcriptional events reported to enhance the MYC pathway activity in both the POLA and TCGA datasets." (PMID 27090007, 2016). "Therefore, an important tumour suppressor pathway is hampered while, at the same time, an oncogene product like c-MYC is stabilized." (PMID 27058426, 2016). "Furthermore, nuclear ADA3 and c-MYC expression together showed significant correlation with tumor grade, mitosis, pleomorphism, NPI, ER/PR status, Ki67 and p27 expression." (PMID 27852327, 2016). "Using multivariate analyses within the whole cohort and the ER+ subgroups, the significant association of ADA3 and c-MYC expression with patients’ outcome was independent of tumor grade, stage and size, and ER status." (PMID 27852327, 2016). "MYC expression profile was also higher in O1 tumours (t-test P value ≤0.013)." (PMID 27090007, 2016). "Tumours clustering as CMS3 were associated with low CIN, moderate WNT/MYC pathway activation." (PMID 27340376, 2016). "The broad range of biological activities of c-MYC, its involvement in a wide variety of human tumours, and its unique ability to regulate a large fraction of the genome have spurred a great interest in the study of the molecular mechanisms involved in the c-MYC-mediated control of gene expression." (PMID 26729287, 2016). "MYC is overexpressed in many tumours and depletion of MYC is known to detain tumour growth." (PMID 27339797, 2016). "Therefore, it must be critical for tumor initiating cells to activate compensatory mechanisms in parallel to MYC activation." (PMID 27282637, 2016). "In addition, data from an in vivo RNA interference screen for tumor suppressor genes in a mouse Eμ-MYC-driven lymphoma model have revealed that downregulation of MEK1 accelerates the development of this disease." (PMID 27741509, 2016). "In addition, both PIM kinases have a reported synergistic effect with c-MYC in mediating tumour development in several cancers, c-MYC gene being translocated to one of the immunoglobulin loci in nearly all BLs." (PMID 26643319, 2015). "MYC represses several miRs with tumor suppressor function by the recruitment of HDACs." (PMID 26416427, 2015). "Two small molecules, JQ1 and iBET, displace BRD4 from acetylated chromatin resulting in downregulation of MYC and modulation of its transcriptional program, including the upregulation of MYC repressed miRNAs, with a marked anti-proliferative cell effect and tumor growth inhibition." (PMID 26416427, 2015). "Further mechanistic studies in such tumor cells are also challenged by the high frequency of concurrent TERT copy number variations, promoter polymorphisms, and cancer-associated dysregulation of factors implicated in TERT regulation such as MYC." (PMID 26194807, 2015). "Given the high incidence of MYC amplification in UM and its correlation with larger tumor size, c-Myc targeting may still represent a possible strategy to manage this disease." (PMID 26397223, 2015). "Heterogeneity of c-MYC GCN gain with respect to tumor location in advanced CRC (cohort 2)." (PMID 26426996, 2015). "We propose that FBXW7 can also act as a tumor maintenance gene in the context of MYC deregulation." (PMID 25669969, 2015). "The fine-tuning of MYC exerted by miR-17-92 in cancer cells guarantees at any given time point a tight control over its transforming activity, with the ultimate goal to sustain tumour maintenance." (PMID 26555894, 2015). "Assessing MYC translocations by determining the partner chromosome and gene, and can also determine whether the tumor has a simple or complex karyotype." (PMID 26416427, 2015). "We specifically investigate proteins with differential abundance between low (non-MYC amplified) and high risk (MYC amplified) group 3 MB tumors, and identify targets that provide insight into the tumor biology of this aggressive subgroup." (PMID 25970789, 2015).
tumor (continued). "We also analyzed the heterogeneity of c-MYC in the primary tumor and distant metastasis." (PMID 26426996, 2015). "Decreased tumor burden, involving simultaneous MYC and IRF4 downregulation and apoptosis induction." (PMID 25849938, 2015). "This provides evidence for an essential role of MYC/miR-17-92 FFLs throughout tumour development." (PMID 26555894, 2015). "MYC regulates many functions, some that promote tumor growth, while others promote apoptosis." (PMID 25890236, 2015). "Inactivation of the MYC oncogene in mouse models of cancer induces proliferative arrest, apoptosis and/or cellular senescence, as well as the shutdown of angiogenesis; thereby, enabling tumor clearance and sustained tumor regression." (PMID 26412380, 2015). "Furthermore, we confirmed that PTEN expression decreases CAV1/BCAT immuno-complex in murine tumour samples and affects the transcription of known β-catenin targets, MYC and CCDN1." (PMID 26307673, 2015). "Activation of both MYC and eIF4E have been found in human tumor cells." (PMID 25884680, 2015). "For example, oncogenic MYC influences the tumor microenvironment, including suppressing the host immune responses, and MYC inactivation could contribute to tumor regression through the restoration of immune mechanisms." (PMID 26684869, 2015). "From a cancer-biology perspective, we envisage a scenario whereby miR-17-19b maintains cellular homeostasis by protecting cancer cells from exceedingly high and potentially harmful MYC levels, ultimately guaranteeing its ability to sustain continuous tumour growth." (PMID 26555894, 2015). "This anti-tumorigenic effect of MYC may explain the need of other cooperative mechanisms for cell transformation and tumor progression." (PMID 26416427, 2015). "Furthermore luminal tumours express high levels of GATA3 and ER similar to luminal breast cancers and basal like tumours display enhanced MYC and E2F3 pathway signatures." (PMID 26316886, 2015). "MYC is a well-known oncogene, and its function in tumor formation has been intensively studied." (PMID 26198055, 2015). "MYC expression was higher in 19 of the 21 HCC tissues (85.7%) than adjacent non-tumor tissues." (PMID 25749381, 2015). "Examples of known enhancers that displayed DNA methylation changes in these clusters include the tumor-specific hypomethylation of the distal enhancer of MYC (C-5 HMR) that is 67 Kb upstream of the TSS, and the hypermethylation of the enhancer in the second intron of NOTCH1 (A-7 HMR)." (PMID 25706888, 2015). "MYC has been shown to regulate a number of miRs including miR-195 and it has been suggested that repression of anti-tumor miRs may be critical to MYC’s oncogenic activity." (PMID 25750899, 2015). "Moreover, USP22 is required for the proper functioning of MYC, which is widely believed to play a significant role in regulating the tumor cell cycle and tumor invasion." (PMID 25909224, 2015). "We observed significant increase in c-MYC expression in MUC16-positive tumor samples." (PMID 26046375, 2015). "In addition, I-BET762 potently reduced MYC expression in LNCaP prostate cancer cell lines and a patient-derived tumor model with subsequent inhibition of cell growth and reduction of tumor burden in vivo." (PMID 25849938, 2015). "Furthermore, the MYC gene amplification detected in primary tumor cells is mediated by extrachromosomal amplification followed by chromosomal integration; thus the IR/MAR plasmid appears to mimic the episomal model of gene amplification." (PMID 25061979, 2014). "SIRT4 overexpression can prevent MYC-induced glutamine dependency and tumor growth." (PMID 25085992, 2014). "Rather than a direct mutation of MYC, overexpression of this oncoprotein is the major underlying mechanism of action for its tumor-promoting properties." (PMID 25495526, 2014). "It has been reported that the tumor environment down-regulates c-MYC protein levels, which might be a strategy for cancer cells to survive under conditions of limited energy resources." (PMID 24928374, 2014).
tumor (continued). "MYC is a major regulatory factor of stem cell maintenance and tumor cell proliferation." (PMID 24796395, 2014). "Furthermore, we found 4EGI-1 strikingly decreased cell proliferation key regulators cyclin D1 and c-MYC in breast CSC tumor cells, indicating that 4EGI-1 inhibits translation essential for cell proliferation in breast CSCs." (PMID 25115391, 2014). "This interplay between SIRT7 and MYC might suggest that SIRT7 functions as a tumor suppressor by inhibiting MYC activity, similar to SIRT6." (PMID 25085992, 2014). "Consequently, inhibition of MYC-dependent cell transformation by MAX protein is disrupted, causing tumor development." (PMID 24899893, 2014). "Thus, in this cellular context, SIRT6, by regulating HIF1 and/or MYC, qualifies as a tumor suppressor." (PMID 25085992, 2014). "Furthermore, crosstalk has been shown to exist between canonical Wnt signaling and HIF signaling in tumor progression and metastasis via the synergistic interaction of the Wnt target gene c-MYC with HIF-1α." (PMID 25396735, 2014). "Finally, NVP-AUY922/docetaxel combination therapy in mice bearing MYC-CaP/CR tumors resulted in greater anti-tumor activity compared to single treatment." (PMID 25072314, 2014). "Docetaxel treatment did not induce a loss of c-MYC expression (42.3%) compared to vehicle treated tumors (41.2%), which was consistent with AR expression in tumor tissues." (PMID 25072314, 2014). "Nevertheless, there were clear and profound differences between cohorts, as MYC transgenic tumours resolved into fewer clones with substantially greater clonal enrichment compared to other genotypes while the double transgenics showed greater complexity as expected." (PMID 24586197, 2014). "To test whether progression RIS targets were also selected by their high transcription rates in premalignant cells, we compared the transcriptomes of Runx2/MYC and control thymus at 10 days of age, several weeks before clonal tumours emerge." (PMID 24586197, 2014). "MYC over-expression was significantly associated with tumor stage and MMR/BRAF IHC phenotype, but not gender, anatomic location, histologic grade, presence or absence of lymphovascular space invasion, nor peritumoral lymphocyte reaction status." (PMID 24503701, 2014). "Interestingly, the miR-17-92 cluster is positively regulated by c-MYC with which it acts to accelerate tumor development." (PMID 25232701, 2014). "This pathway includes tumor-promoting functions such as those of MYC." (PMID 25288683, 2014). "Importantly, even transient downregulation of MYC has been reported sufficient to diminish the tumor burden in animal models, and the effects of MYC inhibition on normal tissue has been shown to be well tolerated and reversible in adult mice." (PMID 24859015, 2014). "For example, MYC has been shown to directly activate transcription of the oncogenic miR-17-92 cluster and thereby promote cell proliferation, survival, angiogenesis, and metabolic reprogramming in a number of tumor cell lines." (PMID 24550252, 2014). "Furthermore, aberrant activation of MYC expression in cancers provide sufficient energy and anabolic substrates for uncontrolled cell growth and proliferation in the context of the tumor microenvironment." (PMID 24889866, 2014). "The upregulated MYC could then initiate a proliferative program, for instance, through the depicted MYC-E2F interaction, as well as by inhibiting the tumor suppressor miR-29a." (PMID 24968068, 2014). "The MYC-induced DNA damage response acts as a double-edged sword in tumor progression." (PMID 24586676, 2014). "Similar, driver mutations like activation of c-MYC are necessary and sufficient for macrometastasis activation but these mutations are not observed in all tumor types, so can they explain mechanistically global macrometastasis activation?" (PMID 24878664, 2014). "Downregulation of MYC protein was key to tumor response to JQ1 treatment." (PMID 24722523, 2014).
tumor (continued). "The inactivation of MYC can revert the neoplastic phenotype in tumor model." (PMID 23874405, 2013). "Up to date, there is no study correlating MYC mutation, amplification, protein/mRNA levels, and methylation in this neoplasia." (PMID 23717612, 2013). "In this study, we characterized the epigenetic regulation of the pluripotency-associated genes NANOG, OCT4, c-MYC, KLF4, and SOX2 in a variety of cancer cell lines and in primary tumor samples, and investigated the re-activation of pluripotency regulatory circuits in cancer progression." (PMID 24023739, 2013). "In the first example of supervised GSAA, we had demonstrated that the PDGFRB signal transduction pathway (PDGFRB_STP) was differentially regulated by STAT3 and MYC in non-tumor and tumor components, which was supported by our previous studies (and unpublished data of ours)." (PMID 23516564, 2013). "However, reactivation of c-MYC expression in the same animals reinitiates tumor formation in some organs such as breast 92 and pancreas, 93 whereas it induces terminal differentiation or apoptosis without tumor regrowth in others 94,95." (PMID 23634284, 2013). "ERK mediated MYC phosphorylation is also activated by oxidative stress in tumor cells." (PMID 24236059, 2013). "The involvement of NF-kB and IP3K pathways might have implication for the development of therapies against MYC-positive tumours." (PMID 24079473, 2013). "MYC may have a dual function in cancer cells, i.e. it can promote cell proliferation or induces apoptosis depending on molecular background and tumor microenvironment." (PMID 23555992, 2013). "Decreased euchromatic regions have also been identified in tumor models when MYC is knocked down." (PMID 23373009, 2013). "Thus, diclofenac targets tumor cell proliferation via two mechanisms, that is inhibition of MYC and lactate transport." (PMID 23874405, 2013). "We evaluated mRNA expression of p16, p21, BMI1 and c-MYC in mice SHR tumor xenografts." (PMID 23342141, 2013). "Downregulation of MYC by diclofenac correlated with tumor cell proliferation." (PMID 23874405, 2013). "First, MYC can promote the expression of epigenetic enzymes, which contribute to tumor development." (PMID 24261995, 2013). "It is believed that elevated MYC signaling amplifies the activity of all expressed genes in a tumor cell, thus sending the cell’s gene expression program into overdrive and dramatically overwhelming any inhibitory factors that might prevent cell proliferation." (PMID 25374893, 2013). "Next we asked whether the lytic activity against splenic targets would also result in an anti-tumor response after immunization with c-MYC protein or single NHPs." (PMID 24130880, 2013). "It was found that the reactivation of the MYC oncogene led to apoptosis of the tumor cells." (PMID 24709643, 2013). "One tumor with high-level MYC gene amplification also showed bi-allelic PTEN gene deletion." (PMID 23289505, 2013). "MYC hypomethylation was associated with diffuse-type, advanced tumor stage, deeper tumor extension, and the presence of lymph node metastasis (p<0.05)." (PMID 23717612, 2013). "Further understanding of molecular mechanisms that determine the role of BET proteins in MYC regulation will help to guide the selection of MYC-driven tumor types that might benefit from BET inhibition therapy." (PMID 24293458, 2013). "A hypomethylated MYC promoter was detected in 86.4% of tumor samples." (PMID 23717612, 2013). "MYC is known to be involved in cell proliferation, apoptosis, differentiation and neoplasia." (PMID 23326503, 2013). "Recent studies assessing global transcription regulated by MYC in normal cells as well as in tumor cells reveal that MYC acts as a direct amplifier of transcriptionally active genes and does not directly induce de novo gene transcription or directly silence expressed genes." (PMID 23373009, 2013).